INS (insulin)
Diseases named in the same sentence as INS in open-access papers (continued):
Sharing a sentence is not in itself a finding about the gene and the disease.
diabetes (continued). "Obesity is a risk factor for insulin resistance and T2D, as well as a major risk factor for cardiovascular disease (CVD); however, not all obese patients are insulin-resistant or at high risk of diabetes and CVD." (PMID 32161549, 2020). "Knowing that zinc in insulin formulations may induce generalized allergy may help physicians better tailor diabetes management therapy." (PMID 32584876, 2020). "Further investigations are needed to better understand the lack of response to insulin in T2D pregnancy and the clinical implications of theses immunological parameters in the monitoring of complications associated with diabetes during pregnancy." (PMID 32626786, 2020). "In the current study, ZBPYR significantly improved the chronic activation of the HPA axis, reduced blood glucose concentrations, promoted insulin sensitivity, slowed the progression of diabetes, as well as enhanced exploratory behavior, learning, and memory performance in PSD rats." (PMID 33221746, 2020). "However, with chronic hyperglycemia and diabetes, there is a perpetual high demand for insulin, and beta cells become exhausted resulting in insufficient insulin biosynthesis and secretion, i.e., they hypofunction in response to elevated glycemia." (PMID 33182622, 2020). "Our data exhibit that infusion of MSCs and its combination therapy with insulin might ameliorate diabetes signs by changing the amount of leptin and subsequent changes in the expression of neuropeptide Y and melanocortin-4 receptor." (PMID 32405365, 2020). "Furthermore, some researchers wonder if behaviors such as body checking in cancer patients or injecting lower than the prescribed insulin dose in diabetes patients should be part of the definition of HA in this context." (PMID 32716932, 2020). "Synbiotic is a combination of probiotic and prebiotic that may be beneficial in the treatment of diabetes through modulating serum insulin levels." (PMID 32509880, 2020). "In ARIC, NEFAs was an independent predictor of diabetes and thus might play a mediating role; the hypothesized mechanisms focused on the involvement of an impaired insulin signaling pathway." (PMID 33142938, 2020). "In this context, supplementation with turmeric (Curcuma longa L.), in different ways, appears to act beneficially on glycemic control; these effects are partly due to an attenuation of insulin resistance and frequently encountered comorbidities in patients with diabetes." (PMID 32774865, 2020). "Moreover, TZQ was found to significantly regulate abnormal glucose, decrease insulin secretion to maintain normoglycaemia, and reduce glycosylated haemoglobin (HbA1c) and fasting insulin in type 2 diabetes mellitus patients." (PMID 33208112, 2020). "Since insulin and amylin are co-secreted and in most of cases of diabetes mellitus (particularly Type I diabetes mellitus), there is a decrease in insulin levels, therefore, hyperamylinemia may not be present in all diabetic patients." (PMID 32436936, 2020). "Stage 1 is the compensation stage, which occurs during diabetes progression, whereby β-cell adaptation increases in the β-cell area in the pancreas in order to upregulate insulin secretion in response to the increased demand for insulin." (PMID 32375753, 2020). "Decreased insulin sensitivity and incidence of diabetes mediated by elevated WBC count may partly explain this association." (PMID 33679598, 2020). "Mean (SD) preoperation HbA1c levels were slightly lower (7.0% [1.1%]) vs 7.2% [1.3%]) as was the mean (SD) number of diabetes medications (1.5 (1.1) medications vs 1.7 [1.1] medications) and insulin use (2317 of 6141 [37.7%] vs 4692 of 9710 [48.3%]; eTable 4 in the Supplement)." (PMID 32129809, 2020). "Diabetes mellitus is a metabolic disorder that results from disturbances in insulin secretion, insulin action, or both, and leads to chronic hyperglycemia with defects in carbohydrate, lipid, and protein metabolism, as defined by the World Health Organization (WHO)." (PMID 33437546, 2020).
diabetes (continued). "Moreover, in ob/ob mice (well-established models of human type 2 diabetes mellitus (DM2)), PANK1 deficiency leads to reduced serum insulin, improved insulin tolerance, and reduced fasting blood glucose." (PMID 33260564, 2020). "Pulmonary insulin is gradually rising as a new approach for the treatment of diabetes mellitus." (PMID 32850233, 2020). "The changes in diet, and potentially increasing insulin sensitivity that can lead to remission of type 2 diabetes mellitus, are necessary to prevent hypoglycemia or the prolonged use of drugs that may no longer be directly beneficial." (PMID 33178530, 2020). "Moreover, very high overactivity of active SREBP-2 peptide in PBCs induces low weight, lower PBC mass, death and impaired insulin secretion in mice, which develop severe diabetes." (PMID 33066385, 2020). "Furthermore, 66.8% of physicians strongly agreed that each hospital institution should have a structured diabetes program for patients who are using insulin pumps." (PMID 33334003, 2020). "However, we showed for the first time that serum ucOC is positively correlated with IGI, which reflects insulin secretion in early phase, in individuals with diabetes." (PMID 32821293, 2020). "In addition to insulin, endocrine hormones, especially thyroid hormone, also play an important role in the pathogenesis of diabetes." (PMID 32714391, 2020). "The insulin/IGF signalization plays an important role in diabetes." (PMID 33101198, 2020). "Additionally, their insulin resistance increases steadily from non-diabetes to pre-diabetes and to diabetes, a stark difference compared to the trend seen in the overall population, where insulin resistance peaks in pre-diabetes." (PMID 33261162, 2020). "However, blood glucose (fasting and non‐fasting), glycated hemoglobin, insulin and triglyceride levels showed little difference between the diabetes mellitus + vehicle group and diabetes mellitus + exenatide group." (PMID 31199578, 2020). "However, we attempted to alleviate this bias by limiting the analysis to a population of patients with diabetes (using non-insulin antidiabetic agents as proxy), which presumably share at least a set of common risk factors." (PMID 32938499, 2020). "The insulin-sensitizing, anti-diabetic, anti-atherogenic, and anti-inflammatory properties of adiponectin suggest its potential relevance as a therapeutic target for diabetes and metabolic syndrome." (PMID 32915782, 2020). "Finally, it has been described that in mice with STZ-induced diabetes, insulin-dependent translocation of Glut4 to plasma membranes of hippocampal neurons was affected." (PMID 32789766, 2020). "Treatment for diabetes (insulin) and high blood pressure (perindopril) was also started." (PMID 32687026, 2020). "Failure to inject insulin on time may lead to serious diabetes complications such as diabetic ketoacidosis (DKA), cardiovascular diseases, blindness, stroke and neurasthenia." (PMID 33291519, 2020). "Additionally, duration of diabetes mellitus and preoperative insulin treatment are strong predictors of achieving complete remission after the surgery." (PMID 33298009, 2020). "This suggests that in humans, ucOC may play more important roles in insulin secretion than in insulin sensitivity in individuals with diabetes." (PMID 32821293, 2020). "Poor diet control, improper treatment with insulin and hypoglycemic drugs, and inadequate compliance are associated with blood glucose fluctuation during the course of T2DM; thus, glucose fluctuations are difficult to avoid in patients with diabetes." (PMID 32943002, 2020). "Patients with diabetes often have increased levels of circulating insulin, which may also increase growth and proliferation of cancer cells." (PMID 33437503, 2020). "All nine patients had type-2 diabetes mellitus on insulin treatment regimes." (PMID 33409023, 2020).
diabetes (continued). "However, we estimated the potential bias from informative censoring due to diabetes and death using shared parameter models and deemed the associated bias to be minimal, suggesting that the observed results may underestimate the annual rate of change in insulin resistance indexes." (PMID 31992297, 2020). "However, this scenario is very different for people with diabetes who suffer from insufficient levels of insulin." (PMID 32106464, 2020). "MoCA score was considered the dependent variable, and age, sex, education level, diabetes duration, insulin use, BMI, HbA1c, FBG, PBG, TC, TG, LDL-C, HDL-C, ApoA1, ApoB, and sLRP1 were considered the independent variables in the multiple linear regression analysis." (PMID 33013281, 2020). "Thus, we argue that defective oxidative glucose metabolism is central to beta cell failure in diabetes, acting both at the level of single beta cells and potentially across the whole islet to impair insulin secretion." (PMID 32894309, 2020). "In fact, resistin could be considered a linking hormone between obesity and diabetes (“resistin” indicates resistance to insulin)." (PMID 32660156, 2020). "It has been established that disruption of insulin signaling is a major etiology of neuronal diseases such as Alzheimer’s and Parkinson’s diseases and that brain neuronal diseases, diabetes mellitus, and obesity are closely connected, and neurodegeneration is triggered by insulin signaling." (PMID 32575897, 2020). "Significant differences were found between individuals with NGT, pre-diabetes and T2D, where individuals with T2D were older (p < 0.001), had higher WC (p < 0.001), fasting plasma insulin (p < 0.001), systolic and diastolic blood pressure (p < 0.001) and serum triglycerides (p < 0.001)." (PMID 32397403, 2020). "Although the baseline hyperglycemia decreases in some patients with time, patients may use a variety of oral medications and insulin to control their diabetes post-operatively." (PMID 33178530, 2020). "Other studies have observed that the use of metformin, in combination with B420, might bring much better results in the treatment of diabetes, i.e., improved glycaemic control and insulin sensitivity." (PMID 32013181, 2020). "In diabetes, cAMP plays a very critical role in insulin secretion." (PMID 33905469, 2020). "Additionally, stress was related to greater diabetes mellitus distress, lower diabetes mellitus empowerment, greater insulin use, and poorer glycemic control." (PMID 33355538, 2020). "For PP, there has not been any decisive consensus as to whether this hormone contributes to energy homeostasis and diabetes by directly regulating insulin production, action, or both." (PMID 32371554, 2020). "Diabetes mellitus (DM) is a heterogeneous metabolic disorder characterized by the presence of hyperglycemia due to impairment of insulin secretion, defective insulin action, or both, which requires continuous medical care with multifactorial risk-reduction strategies beyond glycemic control." (PMID 33170882, 2020). "Recently, insulin resistance has been related to asthma like symptoms and this might enlighten our knowledge about insulin effect in normal individuals compared to those who develop diabetes." (PMID 32117245, 2020). "•The efficacy of insulin therapy in diabetes depends on proper injection technique." (PMID 32071879, 2020). "We observed that the co-payment level increase of antidiabetic medications had the strongest, immediate average effect on glycaemic control among those who were utilizing only other diabetes medications than insulin or metformin at the time of the policy change." (PMID 33246453, 2020). "The study named Efficacy and Safety of Degludec versus Glargine in Type 2 Diabetes (DEVOTE; CT.gov identifier: NCT01959529), a trial involving 7637 patients with stated CVD and a mean diabetes duration of 16 years, confirmed the CV safety of insulin degludec when compared with insulin glargine." (PMID 32225082, 2020).
diabetes (continued). "In the second scenario, reduced vitamin B6 levels might trigger diabetes onset by impacting the insulin secretion or its biological activity." (PMID 32456137, 2020). "Interestingly, organismal injury and abnormalities, insulin resistance in the liver, endocrine system disorders, diabetes mellitus, and autophagy of muscles were the diseases most significantly linked to the DE miRNA target genes." (PMID 32664305, 2020). "It has been reported that in diabetes, restoration of β cells could result from reprogramming of pancreatic δ cells into insulin producers." (PMID 33250773, 2020). "For example, let-7d could reduce insulin secretion and impair glucose tolerance;15 here it was significantly upregulated in the diabetes-VS-normal comparison and downregulated with the DFE administration." (PMID 31790971, 2020). "In addition, recent studies emphasized the success of online video-based CME on improving knowledge of primary care physicians related to diabetes management and insulin therapy." (PMID 33081765, 2020). "It is still debatable whether insulin directly affects the outcome or whether it is merely a marker of advanced diabetes." (PMID 33113760, 2020). "Addition of HbA1c (mmol/mol), insulin use (n, %) and diabetes duration (years) to the multivariate logistic regression model for CVD did not materially change the standardized Beta (95% CI) for the association of the Z-score of log calprotectin with CVD (1.356 (1.037–1.773), p = 0.026)." (PMID 33138021, 2020). "Increased inflammation induced by H. pylori infection could lead to insulin resistance and diabetes through a sex-dimorphic hypothalamic insulin action." (PMID 33062714, 2020). "In adolescents and adults, beta cell hypersecretion of insulin, in the absence of insulin resistance, was later linked to impaired glucose tolerance and diabetes." (PMID 33158303, 2020). "Diabetes is a clinically heterogeneous, chronic condition characterised by a failure to maintain normal glucose levels through conversion of food into energy via insulin-dependent mechanisms." (PMID 32797243, 2020). "Given that insulin therapy has an optimal glucose-lowering effect in patients affected by diabetes, it is suggested that insulin is the treatment of choice in hospitalized COVID-19 patients with diabetes." (PMID 33335527, 2020). "In univariate analyses, insulin clearance was significantly associated with cIMT in participants with newly diagnosed (ßst = − 0.39; p = 0.03) and without diabetes mellitus (ßst = − 0.11; p = 0.03) as well as IFG (ßst = − 0.27; p = 0.01)." (PMID 33384433, 2020). "PDA genesis, insulin secretion, and diabetes pathways confirm the accuracy of our analysis." (PMID 32245227, 2020). "However, the primary aim of this study was not to test the effect of IX10 and HI in the most representative model of cancer in people with diabetes, but to explore the mechanisms which potentially increase the growth-potential of insulin analogues." (PMID 32350367, 2020). "If they are used in patients with diabetes, hyperglycaemia may worsen, necessitating escalation of insulin therapy." (PMID 32405783, 2020). "Obesity damages mitochondrial function, which could be one of many defects linking obesity to diabetes, by decreasing insulin sensitivity and compromising β-cell." (PMID 33375647, 2020). "In summary, results of the studies clearly acknowledge that isoflavonoids favorably affect several aspects of diabetes-induced metabolic disorders and modulate carbohydrate metabolism, glucose homeostasis, insulin secretion, and insulin resistance as well as β islet pancreatic cell protection." (PMID 33255206, 2020). "First, diabetes leads to muscle weakness due to insulin resistance and glucose toxicity." (PMID 33002067, 2020). "Meanwhile, insulin sensitivity improved in those with a relatively short diabetes duration." (PMID 32025522, 2020).
diabetes (continued). "The decrease in insulin secretion, especially in people with impaired glucose tolerance, may partly explain the effect of advanced age on diabetes and prediabetes." (PMID 33679598, 2020). "The propensity of insulin to fibrillate, can cause, besides pathological, also biomedical and biotechnological complications of high relevance, considering its wide therapeutic use in diabetes treatment and the requirement of functional insulin in each pharmaceutical dose." (PMID 32414105, 2020). "Air pollutants may contribute low-grade inflammation and oxidative stress, pancreatic disruptions, decreased insulin signaling, glucose metabolism impairment, insulin resistance, and type 2 diabetes mellitus." (PMID 32512868, 2020). "Thirty percent of patients with diabetes were treated with insulin." (PMID 33179989, 2020). "However, marked improvement in insulin availability in East Africa now challenges this assumption and raises questions about the quality of insulin and other essential diabetes therapies, as diabetes metabolic control is still unacceptably poor." (PMID 32704558, 2020). "Holding other variables constant, the odds of depression is increased by 24.46 times (HPD CI: (15.20, 49.37)) among diabetes patients who are taking both oral antidiabetic medication and insulin as compared to those are taking only oral antidiabetic medication." (PMID 33145110, 2020). "This is the first investigation with clear evidence that the OLE, as a potential insulin stimulator, can be used for the treatment of diabetes via the improvement of intracellular GLUT4 translocation in the skeletal muscle by the activation of Rab8A and Rab13 proteins." (PMID 33256066, 2020). "It was demonstrated that daily administration of rutin 25-100 mg/kg for 45 days could enhance insulin secretion and reduce fasting blood glucose concentrations in streptozotocin-induced diabetes in rats." (PMID 33299532, 2020). "Hypoglycemia that may occur during fasting and during treatment of diabetes with insulin must be avoided to maintain intact cerebral functions." (PMID 32789766, 2020). "The current study provided a novel strategy and a scientific mechanism of action for the use of PA flower as a prophylactic and an alternative medicine in the treatment of diabetes mellitus due to its antioxidant, anti-inflammatory, hypolipidemic, hypoglycemic and insulin secretagogue effects." (PMID 32967670, 2020). "Cardiac metabolic inflexibility, characterized by impaired insulin-induced glucose uptake and oxidation, has been reported as an early and consistent change in the heart of different models of MetS and diabetes; however, the evaluation of Akt activation has yielded variable results." (PMID 31995605, 2020). "The detection of microevents as the name suggests is carried out at an individual level by tracking the individual’s diabetes profile including blood glucose levels, amount of insulin injections, carbohydrate consumption, physical activity or exercise sessions, and others." (PMID 32784178, 2020). "GIPET-1 is currently used in tablet form of insulin with three different coatings and has been studied for its pharmacokinetics and pharmacodynamics properties towards the treatment of diabetes mellitus and is currently the subject of a Phase I clinical trial (NCT01931137)." (PMID 33352795, 2020). "In case of a new diagnosis of diabetes, a mediterranean dietary regimen was suggested as first-line approach, an addition of metformin therapy and/or long-acting insulin was preferred as second-line approach, whereas the addition of a short-acting insulin was selected as third-line approach." (PMID 31313243, 2020). "Nevertheless, the levels of total AV+ cMVs were numerically lower in the diabetes subjects, and one might speculate if it results from the effects of frequent acute insulin exposure on the vascular endothelium, beyond the glucose-lowering ability." (PMID 32309448, 2020).